CAT (catalase)
Diseases named in the same sentence as CAT in open-access papers (continued):
Sharing a sentence is not in itself a finding about the gene and the disease.
diabetes (continued). "Lens observations and determination of hepatic MDA and GSH concentrations and SOD, CAT, GSH-Px, and GR activities from our experiment showed the extent of damage to the lenses and livers of rats caused by diabetes mellitus." (PMID 37999206, 2023). "Our findings show that the GPx, SOD, and catalase levels were remarkably lower (p < 0.05) after the induction of diabetes." (PMID 37513325, 2023). "Field cricket glycosaminoglycan has regulated diabetes by significantly increased CAT, SOD and GSH-Px content in db mice." (PMID 37497112, 2023). "In diabetes situations, the CAT activity and SOD values deteriorate due to unregulated production of hydrogen peroxide-induced by lipid peroxidation, protein glycation, and glucose autoxidation." (PMID 37280499, 2023). "Reduction of CAT activity is recognized as one of the factors that contribute to the occurrence of damage mediated by oxidative stress in diabetes and other degenerative diseases." (PMID 36829941, 2023). "The causation of elevated and unchanged levels of SOD and CAT could be linked to the overexpression of these enzymes to get rid of oxidative attack and peroxidation of polyunsaturated fatty acids in the cell membrane of patients with diabetes so that free radicals are compensated." (PMID 37432193, 2023). "GRb1 treatment significantly reduced ROS, cell death, MDA levels and CAT activity in diabetes larvae." (PMID 36355094, 2022). "ROS, cell death, MDA levels and CAT activity were significantly increased in diabetes larvae compared to the control group, while riboflavin intervention reversed their increases." (PMID 36355094, 2022). "Diabetes mellitus is associated with a significant failure of antioxidant machineries (SOD, CAT, and GSH) in liver tissues, resulting in oxidative stress." (PMID 36552606, 2022). "In the hippocampal tissue of diabetes group, a considerable reduction of CAT activity was observed in comparison to the control ones (p<0.001)." (PMID 35614890, 2022). "Diabetes also resulted in a significant reduction in CAT activity in cortical tissue compared to the control group (p<0.001)." (PMID 35614890, 2022). "The results showed that these extracts restored the levels and activities of glutathione, catalase, superoxide dismutase, glutathione peroxidase, aspartate aminotransferase, alanine aminotransferase, and alkaline phosphatase to the state before diabetes." (PMID 35885378, 2022). "It has also been documented that, in STZ-induced diabetes in animal models, a decline in CAT and SOD level encounters in brain occurs." (PMID 35458597, 2022). "Given that increased CAT activity in diabetic rats (D group) is a compensatory response against diabetes-induced oxidative stress, so treatment with curcumin and metformin probably modulated this response through their antioxidant capacities." (PMID 35935389, 2022). "A lower level of CAT activity in plasma was observed in patients with diseases related to oxidative stress, such as diabetes mellitus (type I and II), neurodegenerative diseases, cancer, and anemia." (PMID 35744968, 2022). "In a previous report, a medicinal plant Peganum harmala used in the treatment of various diseases such as diabetes, depression, cough, and some other human ailment divulged lower catalase activity (555 U/g) compared with the present finding." (PMID 36311077, 2022). "Elevated ROS levels in diabetes partially result from decreased production of potent antioxidants, including CAT, SOD, and GPX." (PMID 36078578, 2022). "CAT is one of the major intracellular antioxidant enzymes, which has been found to help alleviate autophagy in mice with cardiac injuries induced by diabetes." (PMID 36275675, 2022). "The tissue ROS level is high in diabetes due to decrease or/and increase in catalase (CAT), superoxide dismutase (SOD), and glutathione peroxidase (GSH-Px) production." (PMID 36124067, 2022).
diabetes (continued). "Low activity of CAT in the blood was observed in patients with atherosclerosis and diabetes, which indicates long-lasting OS in the cells of the body of these people." (PMID 35207512, 2022). "With diabetes, this vasodilation was partially blunted, and the remaining vasodilation was abolished by catalase and wortmannin." (PMID 36613929, 2022). "Data similar to ours was reported by a recent study that compared the salivary levels of some markers of oxidative stress: TOS, MDA, the level of thiol groups and total antioxidant capacity, uric acid, peroxidase and catalase in subjects with diabetes." (PMID 34829612, 2021). "The colorimetric method showed that the retinal and plasma levels of CAT increased significantly after an early (5-day) onset of diabetes when compared to normal controls." (PMID 34440748, 2021). "In rabbits, camel milk normalized the level of free radicals arising from oxidative stress caused by diabetes by increasing antioxidant genes (SOD and CAT)." (PMID 34067516, 2021). "STZ‐induced diabetes increased urea and creatinine levels and decreased CAT and SOD levels significantly (p ≤ .05) compared to the control group." (PMID 34531994, 2021). "In conclusion, we have demonstrated that several layers of the retina contain incretins and catalase, and that the retinal levels of these molecules increase significantly in early diabetes." (PMID 34440748, 2021). "The contents of lipid peroxidation and protein oxidation products, the activity of catalase, and glutathione peroxidase (GPx) were increased in the plasma of rats with diabetes mellitus." (PMID 34573031, 2021). "Previous research on a medicinal plant known as Peganum harmala used in the treatment of some disease e.g. cough, diabetes, depression, and some other human ailments, revealed lower catalase activity (555 units/g) than chickpea seeds." (PMID 33927742, 2021). "Our results can be summarized as follows: early (acute) diabetes induces the degeneration of the retina, which results in increased incretins and catalase production and increased retinal cellular bioenergetics." (PMID 34440748, 2021). "In both types of diabetes, the cardiac expression of catalase and manganese sodium dismutase (MnSOD) proteins were reduced—exenatide significantly increased expression of MnSOD in T1D and T2D and catalase in T2D." (PMID 34639160, 2021). "For example, it has been reported that apocynin counteracts the reduction of superoxide dismutase (SOD), catalase (CAT) and glutathione (GSH) in an in vivo model of myocardial injury and diabetes-associated cognitive decline." (PMID 34203655, 2021). "The increased catalase activity in patients with diabetes has been attributed to protective and adaptive mechanisms that develop in tissues in response to oxidative stress." (PMID 32512870, 2020). "Recent studies have confirmed that impairment of catalase, a major antioxidant enzyme, can aggravate diabetes-induced cardiac toxicity." (PMID 33014281, 2020). "In humans, it is unclear whether catalase deficiency is associated with obesity; however, this seems to be true, at least partially, as demonstrated by the cautious lifestyle lead by these patients to prevent complications from acatalasemia, including diabetes." (PMID 33080438, 2020). "Glycation of SOD and CAT, which occurs in diabetes, or inactivation of SOD by H2O2, leads to a reduction in enzyme action." (PMID 33367177, 2020). "Since pancreatic beta cells are vulnerable to oxidative stress due to low expression of antioxidant genes such as superoxide dismutase and catalase, the prevention of ROS production is an important therapeutic strategy for diabetes." (PMID 32397640, 2020). "An upregulation of the Nox4 expression with downregulation of the catalase expression and/or activity in diabetes increases the hydrogen peroxide concentration which promotes retinal neovascularization through the VEGF signaling pathway." (PMID 31827713, 2019).
diabetes (continued). "The decrease of catalase levels has been previously reported in experimental diabetes induced by STZ in rats." (PMID 30818888, 2019). "Other issues in diabetes including nephropathy, retinopathy, neuropathy, and vascular damage possibly correlate with a deficit in erythrocyte catalase, which removes H2O2 from tissues." (PMID 31510091, 2019). "n-3 PUFA increased the activity of SOD and it also increased the activity of CAT, which reduces intracellular ROS and inhibits oxidative damage, preserving its protective role in diabetes development." (PMID 31340612, 2019). "Considering the antioxidant stress property of FSM, the effects of this compound were evaluated on serum GSH-Px, SOD, and CAT activities after 42-d treatment (72 d of total duration of diabetes)." (PMID 31396288, 2019). "It has suggested that CAT-21A/T (rs7943316) OMIM: 115500 gene promoter polymorphism is predominantly associated with different human disorders such as hypertension, cancers, diabetes, nephropathy, and other diseases accompanied by oxidative stress." (PMID 29492090, 2017). "Catalase overexpression also prevented the diabetes‐induced increase in levels of the apoptotic marker cleaved caspase‐3, especially at the 8 week time‐point." (PMID 28643395, 2017). "We injected the autophagy inhibitor 3‐MA and the autophagy activator rapamycin into WT diabetic mice and CAT‐TG diabetic mice, respectively, for up to 8 weeks after the induction of diabetes." (PMID 28643395, 2017). "After several more weeks, the number of autophagy puncta increased, and catalase overexpression inhibited diabetes‐induced LC3‐II expression." (PMID 28643395, 2017). "Echocardiography showed that 3‐MA partially reversed the diabetes‐induced reductions in cardiac function, whereas the autophagy activator rapamycin impaired the protective effect of catalase overexpression on the diabetic heart." (PMID 28643395, 2017). "Upregulation of catalase activity has also been reported in serum and erythrocytes from subjects with diabetes." (PMID 28545081, 2017). "In rats with induced diabetes, Zinc and curcumin treatment showed a significant increase of catalase and a significant decrease of glucose, lipid profile components and arylsulphatases activity compared to the untreated rats." (PMID 28293546, 2017). "ROS accumulation was elevated in the hearts of WT diabetic mice, while overexpression of the ROS scavenger catalase significantly decreased diabetes‐induced ROS accumulation." (PMID 28643395, 2017). "The increased activities of serum SOD and CAT due to Vit-C treatment, apparently, resulted in the amelioration of the toxic effects of the ROS, generated in excess during diabetes." (PMID 27164129, 2016). "Enhancement of SOD and CAT activities were observed in PSEE-treated 8-week diabetic retina with a dose-dependent manner." (PMID 27649243, 2016). "Our data demonstrate that GST participates in all phases of prostatic tissue in response to disease but early responses also involve the activation of GPx, whereas CAT activation occurs at later stages of untreated diabetes." (PMID 26064423, 2015). "In the ventral prostate, the CAT activity was unchanged in the groups of the first experiment, but doubled after two months of diabetes compared with the control group and this increase was prevented by MLT treatment." (PMID 26064423, 2015). "In prostate, melatonin administration normalized GST activity at both ages and mitigated GPx at short-term and CAT at long-term diabetes." (PMID 26064423, 2015). "In the present study, SOD and CAT showed lower activities in liver during diabetes and the results agree well with the earlier published data." (PMID 25561940, 2015). "In our recent study, we have demonstrated that expression levels of catalase and glutathione peroxidase were suppressed with diabetes." (PMID 25905778, 2015).
diabetes (continued). "Prostate exhibited a 3-fold increase in GPx activity at short-term diabetes and at long-term diabetes there were 2- and 3-fold increase in CAT and GST, respectively (p ≤ 0.01)." (PMID 26064423, 2015). "The decreased activities of GSH, SOD, and CAT on induction of diabetes were significantly (p < 0.05) reversed on feeding with the formulated biscuit." (PMID 26713163, 2015). "STZ diabetes in G2 rats showed also an increase in lipid peroxidation and IL-6 and decreased catalase, SOD, and GSH activity in the serum and the kidney tissue homogenate compared with that of the negative control group." (PMID 25629046, 2015). "A significant (p < 0.05) decrease in the activities of glutathione (GSH), superoxide dismutase (SOD), and catalase in the hepatic tissue was also observed on induction of diabetes." (PMID 26713163, 2015). "Diabetes increased oxidative stress as lipid hydroperoxide concentration was higher and the activity of antioxidant enzymes superoxide dismutase, catalase, and glutathione peroxidase was lower in DM-Sed than C-Sed." (PMID 26509175, 2015). "On the other hand, test compounds significantly prevented the diabetes-induced decrease in catalase activity." (PMID 25548795, 2014). "Similar changes were also recorded for CAT activity in diabetes groups, whereas GSH-Px activity was markedly decreased in diabetic rats compared to the normal rats." (PMID 24939518, 2014). "Diabetes promoted an increase in CAT activity (DMI: 0.62 ± 0.1; D: 0.56 ± 0.09 vs. IM: 0.35 ± 0.02 and C: 0.29 ± 0.05 nmol/mg protein)." (PMID 25301475, 2014). "In the present study, significant decline in GSH level and antioxidant enzymes activity including SOD and CAT in the hippocampal tissue of rats reflects oxidative stress of hippocampus in experimental diabetes." (PMID 25114929, 2014). "Naringenin, a flavonoid, was able to restore the modulation seen in SOD, Catalase, GPx activity and redox ratio due to diabetes induction." (PMID 28962270, 2014). "Diabetes also slightly up-regulated the expression of p-Nrf2 protein and the expression of Nrf2-downstream antioxidant genes: CAT and NQO-1." (PMID 24720784, 2014). "STZ induced diabetes also showed significant increase in the antioxidant enzymes catalase in cardiac tissue compared with controls (172.2500±7.7170 vs. 54.6170±3.0170 U/mg protein, n = 6, P<0.001)." (PMID 23843977, 2013). "The antioxidant enzymes usually studied in diabetes include catalase, superoxide dismutase, glutathione system, and thioredoxin system." (PMID 26317017, 2013). "In diabetes, the activities of CAT and GPx are significantly decreased by superoxide radical and by glycation reactions." (PMID 24167738, 2013). "In ourinvestigation the SOD and CAT significantly decreased the diabetes as a result ofnon-enzymatic glycosylation and oxidation." (PMID 24349947, 2013). "Reduced activities of SOD and catalase in the liver and pancreas during diabetes were reported, resulting in a number of deleterious effects due to the accumulation of superoxide radicals and hydrogen peroxide." (PMID 23834750, 2013). "The reason why the increase in HO-1 was accompanied by an increase in catalase is because up-regulation of HO-1 renders the cells resistant to diabetes-induced oxidative stress by increasing other antioxidant genes, including catalase." (PMID 23843977, 2013). "In diabetes- induced rats, free radical scavenger enzymes were measured, and decreases in the activities of glutathione peroxidase, catalase, and superoxide dismutase were observed." (PMID 23762597, 2013). "And previous studies showed that HO-1 against oxidative stress requires an increase in Sod and catalase in experimental diabetes, we also detect the change of some oxidative stress-responsive genes." (PMID 24255720, 2013).
diabetes (continued). "Some lens parameters, including glycated proteins, AGEs, SOD, and AR activities, were increased while some others, including soluble and total protein, GSH level, and CAT activity, were decreased due to diabetes induction." (PMID 22355255, 2012). "For example, overexpression ofH2O2-scavenging enzymes catalase and glutathioneperoxidase actually sensitizes mice to insulin resistance and diabetes." (PMID 21249230, 2011). "In lieu with GPx, the catalase activities were also decreased in diabetes compared to control subjects." (PMID 17603912, 2007). "Furthermore, catalase overexpression attenuated intrarenal AGT expression in an animal model of diabetes." (PMID 40362266, 2025). "The catalase pathway of ethanol metabolism will be more prominent under the conditions of fasting, diabetes, high‐fat diet feeding, and hypolipidemic drug treatment when peroxisomal β‐oxidation is upregulated, which will accelerate ethanol oxidation and acetaldehyde release." (PMID 40496347, 2025). "Vitamin C increases catalase activity in the liver of rats with diabetes." (PMID 40943563, 2025). "Therefore, it is of interest to investigate the activity of antioxidant enzymes (SOD, CAT and GPx) in patients with Type 2 Diabetes Mellitus (T2DM) to understand the relationship between glycemic control and oxidative stress." (PMID 41907928, 2025). "The results of a study also highlight that p-coumaric acid is an efficient compound with antioxidant properties and improves the diabetes-induced change in lipid peroxidation and activities of antioxidant enzymes, including catalase, glutathione-S-transferase, and superoxide dismutase." (PMID 40868857, 2025). "We then examined whether anti-miR-200c and CAT treatment improved WH in a mouse model of diabetes (db/db)." (PMID 39948670, 2025). "The diabetes group's CAT activity was much lower than the control group (p < 0.05)." (PMID 39742025, 2024). "Also, the elevation in CAT activity in the treatment groups was markedly higher than in the diabetes group (p < 0.05)." (PMID 39742025, 2024). "A hyperglycemia‐induced increase in oxidative stress is involved in the acceleration of tumor metastasis, and the removal of systemic hydrogen peroxide by glycol‐conjugated catalase can inhibit the progression of diabetic conditions and tumor metastasis in mice with diabetes." (PMID 38009553, 2024). "Biosensor: Evaluation of DPPG-Catalase enzymatic activity to degrade H2O2 via redox reaction to prevent its accumulation and cellular damage associated with neurodegenerative diseases, cancer, or diabetes." (PMID 39330645, 2024). "Moreover, pancreatic antioxidant enzymes, such as superoxide dismutase, glutathione peroxidase, and catalase, exhibit less activity, which leads to enhanced formation of free radicals in diabetes." (PMID 38459494, 2024). "Furthermore, an increase in endogenous antioxidant enzyme activities (GSH, CAT, and SOD) was observed in the groups treated with the supplemented diet, and diabetes causes tissue injury in flies as a result of the increased production of ROS." (PMID 38397536, 2024). "In the majority of diabetes-induced animal studies, V administration was able to regulate oxidative stress biomarkers by restoring enzyme production at normal levels, such as raising catalase or glutathione peroxidase." (PMID 38075040, 2023). "Diabetes is associated with reduced levels of antioxidants, such as glutathione, and antioxidant enzymes, such as glutathione reductase (GR), superoxide dismutase (SOD), and catalase (CAT)." (PMID 37761009, 2023). "In addition, a decrease in CAT levels was noted in patients with schizophrenia, diabetes and atherosclerosis." (PMID 37772794, 2023). "Nrf2 activity and expression decrease in diabetes caused by oxidative stress, which can weaken the induction of genes encoding antioxidants, resulting in decreased production of endogenous antioxidants such as SOD, GPx, and catalase." (PMID 36771275, 2023).